DNAJB11 (DnaJ heat shock protein family (Hsp40) member B11)
Description:
As a co-chaperone for HSPA5 it is required for proper folding, trafficking or degradation of proteins. Binds directly to both unfolded proteins that are substrates for ERAD and nascent unfolded peptide chains, but dissociates from the HSPA5-unfolded protein complex before folding is completed. May help recruiting HSPA5 and other chaperones to the substrate. Stimulates HSPA5 ATPase activity. It is necessary for maturation and correct trafficking of PKD1.
Synonyms: ABBP-2; ERdj3; ERj3p; EDJ; ERJ3; HEDJ; ABBP2; DJ9; Dj-9; PKD6; PRO1080; UNQ537
Tractability: Antibody: UniProt predicts a signal peptide or a membrane-spanning region. PROTAC: ubiquitination databases record sites on it; its protein half-life has been measured.
Gene: Protein-coding gene on chromosome 3 (186,567,403 to 186,585,800, forward strand). Ensembl gene ENSG00000090520.
Subcellular location: Endoplasmic reticulum lumen
Subcellular location (Human Protein Atlas): Endoplasmic reticulum
Pathways (Reactome):
Cellular responses to stimuli: XBP1(S) activates chaperone genes
Disease: Maturation of DENV proteins
Gene Ontology:
Molecular function: misfolded protein binding; protein binding; protein folding chaperone; signaling receptor binding
Biological process: positive regulation of ATP-dependent activity; protein maturation; protein folding
Cellular component: endoplasmic reticulum; membrane; protein folding chaperone complex; endoplasmic reticulum lumen; cytoplasm; endoplasmic reticulum chaperone complex; extracellular region; nucleus
Genetic constraint (gnomAD): Loss-of-function variants: 19 observed, 29.9 expected, observed/expected ratio (o/e) 0.64, 90% interval 0.44 to 0.93. The upper end of that interval is the gene's LOEUF score, 0.93, which puts it in group 3 of 6, group 1 being the genes least tolerant of losing a copy. Missense variants: 290 observed, 374.38 expected, observed/expected ratio (o/e) 0.77, 90% interval 0.7 to 0.85. Synonymous variants: 126 observed, 138.15 expected, observed/expected ratio (o/e) 0.91, 90% interval 0.79 to 1.06.
Gene-disease validity (ClinGen):
ClinGen rates the evidence that DNAJB11 causes each of these diseases.
autosomal dominant polycystic kidney disease (autosomal dominant): Definitive. Autosomal dominant form of polycystic kidney disease.
ciliopathy (autosomal recessive): Limited. A genetic disorder of the cellular cilia or the cilia anchoring structures, the basal bodies, or of ciliary function.
Homologues: Orthologues: macaque DNAJB11 (100% identical), chimpanzee DNAJB11 (99% identical), pig DNAJB11 (99% identical), guinea pig DNAJB11 (99% identical), mouse Dnajb11 (98% identical), rat Dnajb11 (98% identical), rabbit DNAJB11 (96% identical), dog DNAJB11 (94% identical), zebrafish dnajb11 (84% identical), Drosophila melanogaster shv (62% identical), Caenorhabditis elegans dnj-20 (56% identical). Paralogues in human: DNAJB5 (32% identical), DNAJB4 (31% identical), DNAJB1 (31% identical), DNAJB13 (26% identical), DNAJB6 (24% identical), DNAJB12 (22% identical), DNAJB2 (22% identical), DNAJB14 (20% identical), DNAJB8 (20% identical), DNAJB7 (20% identical), DNAJB9 (17% identical).
Diseases named in the same sentence as DNAJB11 in open-access papers:
DNAJB11 is named in the same sentence as 44 diseases in open-access papers, as found by Europe PMC text mining. Sharing a sentence is not in itself a finding about the gene and the disease. The quoted sentences say what the papers report.
cystic kidney disease (5 papers, 2020 to 2025). A congenital or acquired kidney disorder characterized by the presence of renal cysts. "More recently, additional ADPKD genes, such as DNAJB11, have been identified and included in the diagnostic routine test for renal cystic diseases." (PMID 38275584, 2023). "Pathogenic variants in the DNAJB11 gene have been recently discovered as a cause of cystic kidney disease." (PMID 38275584, 2023). "About 30% of cystic kidney disease variants were found in patients aged > 75 years, including variants in 4 genes causing ADPKD-like disease spectrum (ALG5, ALG9, DNAJB11, and monoallelic IFT140)." (PMID 40677324, 2025).
autosomal dominant polycystic kidney disease (4 papers, 2021 to 2023). "Heterozygous DNAJB11 variants are associated with autosomal dominant polycystic kidney disease, while biallelic variants cause Ivemark II syndrome or renal‐hepatic‐pancreatic dysplasia syndrome." (PMID 34132027, 2021). "DNAJB11/ERdj3/HEDJ is localized in ER and is associated with glomerular disease, autosomal-dominant polycystic kidney disease, and Gaucher’s disease." (PMID 34948322, 2021). "Autosomal dominant polycystic kidney disease (ADPKD): ADPKD is the most common inherited progressive renal disease caused by the mutation of two major genes, PKD1 and PKD2, and the rare genes, GANAB and DNAJB11." (PMID 37445416, 2023).
pancreatic cancer (3 papers, 2016 to 2022). "Our previous studies have revealed that DNAJB11, a key protein in protein homeostasis, is secreted by exosomes in the supernatant of dissociated pancreatic cancer cells with high metastasis." (PMID 36209075, 2022). "In summary, exosomal DNAJB11 is crucial in maintaining extracellular signaling, altered metabolic behavior, and adhesion properties of pancreatic cancer cells." (PMID 36209075, 2022). "In our study, we found that DNAJB11 reduced the expression of HSPA5 in pancreatic cancer cells." (PMID 36209075, 2022). "The complex relationship between DNAJB11 and TFRC in pancreatic cancer needs to be elucidated in future studies." (PMID 36209075, 2022). "DNAJB11 promoted cancer development through the EGFR/MAPK signaling pathway, providing new insight into the development of pancreatic cancer." (PMID 36209075, 2022). "Our results indicated that CTSD, DNAJB11, and PPT1 were not related with overall survival of pancreatic cancer (data not shown)." (PMID 27869176, 2016).
polycystic kidney disease (3 papers, 2023). A usually autosomal dominant and less frequently autosomal recessive genetic disorder characterized by the presence of numerous cysts in the kidneys leading to end-stage renal failure. "In humans, urinary DnaJB11 is associated with glomerular ER stress, and mutations in DnaJB11 lead to polycystic kidney disease, supporting a role for secreted DnaJB11 in opposing damage linked to extracellular protein aggregation." (PMID 36581212, 2023).
glioblastoma (2 papers, 2021 to 2023). The most malignant astrocytic tumor (WHO grade IV). "Other members have been implicated in cancer development and metastasis, such as DNAJA1 (in glioblastoma and prostate), DNAJB11 (in ovarian tumors), and DNAJC9 (cervical)." (PMID 33810095, 2021). "Proteomic studies reveal nonvesicular release of DnaJB11/ERdj3 from Gli36 glioblastoma cells, but not DKO-1 colon cells, even though it is expressed in both cells." (PMID 36581212, 2023).
hepatocellular carcinoma (2 papers, 2021 to 2022). A malignant tumor that arises from hepatocytes. "Previous studies established that DNAJB11 promotes cancer growth in hepatocellular carcinoma." (PMID 36209075, 2022). "DNAJB11/ERdj3/HEDJ is also upregulated in oral squamous cell carcinoma and hepatocellular carcinoma tissues." (PMID 34948322, 2021).
neuroblastoma (2 papers, 2010 to 2024). Neuroblastoma (NB) is the most common solid, extracranial childhood tumor. "To detect DNAJB11 phosphorylation in response to DNA damage, we exposed epithelial-like 293T and neuroblastoma SH-SY5Y cells to DNA-damaging agent etoposide and ER stress inducer tunicamycin." (PMID 41256008, 2024).
oral cavity squamous cell carcinoma (2 papers, 2016 to 2021). A squamous cell carcinoma arising from the oral cavity. "Interestingly, the human homolog of Shv, DNAJB11, has recently been identified in secretome profiling as a protein upregulated in oral cavity squamous cell carcinoma, as well as secreted during unfold protein response activation." (PMID 27191715, 2016).
breast carcinoma (1 paper, 2022). "In concordance with previous results, DNAJB11 expression is significantly upregulated in breast cancer cell lines than in normal cells." (PMID 36499297, 2022). "High DNAJB11 expression is correlated with poor overall survival, relapse-free survival, and distant metastasis-free survival, implying that DNAJB11 can be used as a prognostic marker for breast cancer patients." (PMID 36499297, 2022).
ciliopathies (1 paper, 2023). "CFAP45 and PROM1 are found in both atypical and secondary ciliopathies, whereas TTC26, SCLT1, DNAJB11, DYNC2LI1, ALMS1, IFT80 and IFT74 are shared between primary and atypical ciliopathies." (PMID 37542408, 2023).
Infertility (1 paper, 2025). "For example, alterations in genes such as SPATA7, DNAH1, DNAI1, and DNAJB11 have been associated with MMAF-related infertility." (PMID 40410177, 2025).
Kaposi's sarcoma (1 paper, 2021). A malignant neoplasm characterized by a vascular proliferation which usually contains blunt endothelial cells. "Intriguingly, DNAJB11/ERdj3/HEDJ, together with HSP90, forms a complex with K1, a transmembrane glycoprotein encoded in the Kaposi sarcoma-associated herpesvirus (KSHV) genome, which is critical for the anti-apoptotic function of K1 in Kaposi sarcoma and other KSHV-related diseases." (PMID 34948322, 2021).
Kidney Cyst (1 paper, 2023). Abnormal fluid filled sac within the kidney, either acquired or congenital. "While DNAJB11 is a known disease-causing gene of ADPKD, and kidney cysts can develop in patients who are heterozygous for a pathogenic variant in PKHD1, more evidence is required to determine whether heterozygous NEK8 and WDR19 pathogenic variants can mimic the ADPKD phenotype." (PMID 36833371, 2023).
membranous nephropathy (1 paper, 2022). "Rats with podocyte diseases (experimental membranous nephropathy and FSGS) showed increases in various glomerular ER chaperones and increased urinary non-KDEL chaperones, including ERdj3 (DNAJB11) and mesencephalic astrocyte-derived neurotrophic factor (MANF), coinciding with proteinuria." (PMID 39086958, 2022).
thyroid cancer (1 paper, 2022). "In contrast, a low level of DNAJB11 mRNA is associated with poor prognosis in thyroid carcinoma." (PMID 36499297, 2022). "Especially the level of DNAJB11 was inversely correlated with the tumor and metastasis stage of thyroid cancer." (PMID 36499297, 2022). "Through bioinformatics analysis using The Cancer Genome Atlas (TCGA) database, DNAJB11 was identified as a tumor suppressor which is downregulated in thyroid cancer tissues compared to normal ones." (PMID 36499297, 2022). "Although the exact tumor suppressive activity of DNAJB11 was not identified, modulation of immune cell infiltration might affect the tumor growth and metastasis of thyroid cancer." (PMID 36499297, 2022).
Viral infection (1 paper, 2021). "All these results suggested that DnaJB11 expression was activated to support P7-1 tubules assembly during viral infection in insect vectors." (PMID 33647067, 2021). "We then performed RNAi assay to explore the roles of DnaJB11 or BAP31 during viral infection in insect vectors." (PMID 33647067, 2021). "Thus, P7-1 of SRBSDV, BAP31 and DnaJB11 formed the complex interaction relationships during viral infection of insect vectors." (PMID 33647067, 2021). "RT-qPCR and western blot assays showed that DnaJB11 expression was significantly increased, while BAP31 expression was significantly decreased at the mRNA and protein levels during viral infection in S. furcifera." (PMID 33647067, 2021). "Here, we reported that two factors of endoplasmic reticulum-associated degradation (ERAD) machinery, the heat shock protein DnaJB11 and ER membrane protein BAP31, were activated by viral infection to mediate the adaptation of S. furcifera to high temperatures." (PMID 33647067, 2021).
cancer (11 papers, 2017 to 2025). A tumor composed of atypical neoplastic, often pleomorphic cells that invade other tissues. "Next, exosomal DNAJB11 contributed to cancer progression, and exosomal DNAJB11 can act as a diagnostic biomarker for PC." (PMID 36209075, 2022). "DNAJB11 is involved in aberrant signaling pathways associated with different cancers." (PMID 37218885, 2023). "The second μ-17-specific cancer-associated module comprises endoplasmic reticulum (ER) molecular chaperones (PDIA4, PDIA6, GANAB) and heat shock proteins (HYOU1, HSPA5, DNAJB11)." (PMID 41373892, 2025). "Concerning cancer, DNAJB11 is endogenously overexpressed in multiple types of human carcinoma cell lines, including Huh7, SH-SY5Y, and HeLa." (PMID 36499297, 2022). "In the DNAJB (HSP40) subfamily, DNAJB11 positively correlated with cell proliferation in 16 cancer types, while DNAJB9 negatively correlated with cell proliferation in 17 cancer types." (PMID 33225964, 2020). "DNAJB11 inhibitors have been proposed as targets to impair the survival of cancer cells." (PMID 36209075, 2022). "DNAJB11 was markedly expressed in most cancers, including PC by UALCAN and GEPIA." (PMID 36209075, 2022). "Importantly, some DNAJB proteins, including DNAJB1/HDJ1, DNAJB4/HLJ1, DNAJB6/MRJ, DNAJB8, DNAJB9/MDG1/ERdj4, DNAJB11/ERdj3/HEDJ, and DNAJB12, are implicated in cancer progression." (PMID 34948322, 2021). "Studies suggest that export of DnaJB11 enhances extracellular proteostasis, that intercellular movement of DnaJB1 or DnaJB6 enhances the proteostasis capacity in recipient cells, whereas the import of DnaJB8 increases resistance to chemotherapy in recipient cancer cells." (PMID 36581212, 2023). "Therefore, the mechanism by which exosomal DNAJB11 promotes cancer cell growth was verified." (PMID 36209075, 2022). "Erdj3 (DNAJB11), a stress-inducible DNAJ homolog, is abundant in the endoplasmic reticulum (ER) and binds to its cellular binding partner, Kaposi sarcoma-associated herpesvirus (KSHV) K1 protein, critically facilitating its partner’s expression and anti-apoptotic function to promote cancer." (PMID 28914774, 2017). "Specifically, DNAJB11 co-localized with AATZ (Z mutant of alpha-1-antitrypsin) protein can induce cirrhosis, increase cancer therapy tolerance, inhibit post-transcriptional degradation of AATZ, and promote tumorigenic AATZ polymer formation." (PMID 36499297, 2022). "The depletion of DNAJB11 increased the possibility of HSPA5 interacting with the unfolded protein and inducing UPR to protect against apoptosis from cancer cells." (PMID 36209075, 2022). "DNAJB11 (ERdj3) is a stress-inducible endoplasmic reticulum (ER) DNAJ homolog that binds to the Kaposi sarcoma-related herpes virus (KSHV) K1 protein, enhances its expression, and shows anti-apoptotic function that promotes cancer." (PMID 38339390, 2024). "Importantly, we revealed that photoactivated ZQX-1 activated HIF1A survival signaling and DNAJB11 mediated survival signaling in A549 cells, though both survival signaling pathways could not compete with oncosis and apoptosis signaling to rescue cancer cells." (PMID 37175463, 2023).
tumor (5 papers, 2020 to 2025). "Their study, which was primarily based on in vitro assays and in vivo mouse xenograft models implanted with human PDAC cells, showed that increased DnaJB11 levels promote tumor growth and inhibit apoptosis, suggesting a tumor-supportive role for this co-chaperone in the PDAC microenvironment." (PMID 41148842, 2025). "Furthermore, immunohistochemical assays showed that DNAJB11 expression was higher than in those injected with shDNAJB11-exo, indicating that exosomes enriched in DNAJB11 increased tumor growth." (PMID 36209075, 2022). "The high DNAJB11 expression levels correlate with tumor size." (PMID 36209075, 2022). "The expression levels of DNAJB1, DNAJB5, DNAJB6, DNAJB11, DNAJB12, DNAJB13, and DNAJB14 were significantly upregulated in the tumor tissues." (PMID 32984053, 2020).
Kidney Disease (3 papers, 2021 to 2024). "First proposed in the 2015 Kidney Disease: Improving Global Outcomes (KDIGO) consensus report, ADTKD is currently believed to be caused by gene mutations UMOD, REN, MUC1, HNF1B, SEC61A, and DNAJB11." (PMID 36362756, 2022).
infection (1 paper, 2014). The state of being infected such as from the introduction of a foreign agent such as serum, vaccine, antigenic substance or organism. "For instance, Dnajb9L2, Dnajb11, Dnajb12b, Dnajc3, Dnajc20, Dnajc21, and Dnajc29 were up-regulated at only one time point (1.5× fold change cutoff); similarly, Dnajb13 was only down regulated at 24h after infection." (PMID 25542027, 2014).
neurodegenerative disease (1 paper, 2024). A disorder of the central nervous system characterized by gradual and progressive loss of neural tissue and neurologic function. "DNAJB11 T188 phosphorylation specifically mitigates α-synuclein aggregation, a protein linked to neurodegenerative diseases." (PMID 41256008, 2024).
DNAJB11 also shares sentences with these, for which no sentence is quoted: autosomal recessive polycystic kidney disease (1 paper); cervical carcinoma (1); cholestasis (1); colorectal cancer (1); congenital anomalies of the kidney and urinary tract (1); congenital dyserythropoietic anemia (1); cyst (1); diabetics (1); gastric cancer (1); Gaucher disease (1); glioma (1); glomerular disease (1); Ivemark II syndrome (1); kidney failure (1); liver disease (1); medullary cystic kidney diseases (1); nephronophthisis 1 (1); nephrotic syndrome (1); neutropenia (1); ovarian tumors (1); polycystic liver disease 1 (1); rectal cancer (1); renal cell carcinoma (1).